LAMP3 (lysosome associated membrane protein 3)
Description:
Lysosomal membrane glycoprotein which plays a role in the unfolded protein response (UPR) that contributes to protein degradation and cell survival during proteasomal dysfunction. Plays a role in the process of fusion of the lysosome with the autophagosome, thereby modulating the autophagic process. Promotes hepatocellular lipogenesis through activation of the PI3K/Akt pathway. May also play a role in dendritic cell function and in adaptive immunity. (Microbial infection) Plays a positive role in post-entry steps of influenza A virus replication, either virus uncoating, cytosolic transport, or nuclear import of viral components, and promotes nuclear accumulation of influenza nucleoprotein/NP at early stages of viral infection. (Microbial infection) Supports the FURIN-mediated cleavage of mumps virus fusion protein F by interacting with both FURIN and the unprocessed form but not the processed form of the viral protein F. (Microbial infection) Promotes the intracellular proliferation of Salmonella typhimuium.
Synonyms: LAMP-3; DC LAMP; CD208; DCLAMP; TSC403; LAMP; DC-LAMP
Tractability: Antibody: UniProt places it where antibodies can reach, with high confidence; its Gene Ontology location is reachable by antibodies, with high confidence; UniProt predicts a signal peptide or a membrane-spanning region.
Gene: Protein-coding gene on chromosome 3 (183,122,200 to 183,163,839, reverse strand). Ensembl gene ENSG00000078081.
Subcellular location: Cell surface; Lysosome membrane; Cytoplasmic vesicle membrane; Early endosome membrane
Subcellular location (Human Protein Atlas): Vesicles
Gene Ontology:
Biological process: negative regulation of proteasomal protein catabolic process; positive regulation of gene expression; regulation of autophagy; regulation of viral life cycle; response to interferon-alpha; symbiont entry into host cell; establishment of protein localization to organelle
Cellular component: cell surface; cytoplasmic vesicle membrane; early endosome; early endosome membrane; lysosomal membrane; perinuclear region of cytoplasm; plasma membrane; vesicle; alveolar lamellar body membrane; late endosome membrane; cytoplasmic vesicle; endomembrane system; membrane
Genetic constraint (gnomAD): Loss-of-function variants: 21 observed, 29.66 expected, observed/expected ratio (o/e) 0.71, 90% interval 0.5 to 1.02. The upper end of that interval is the gene's LOEUF score, 1.02, which puts it in group 4 of 6, group 1 being the genes least tolerant of losing a copy. Missense variants: 462 observed, 507.3 expected, observed/expected ratio (o/e) 0.91, 90% interval 0.84 to 0.98. Synonymous variants: 167 observed, 191.68 expected, observed/expected ratio (o/e) 0.87, 90% interval 0.77 to 0.99.
Homologues: Orthologues: chimpanzee LAMP3 (99% identical), macaque LAMP3 (86% identical), pig LAMP3 (63% identical), tropical clawed frog lamp3 (25% identical).
Diseases named in the same sentence as LAMP3 in open-access papers:
LAMP3 is named in the same sentence as 118 diseases in open-access papers, as found by Europe PMC text mining. Sharing a sentence is not in itself a finding about the gene and the disease. The quoted sentences say what the papers report.
breast cancer (45 papers, 2012 to 2025). A primary or metastatic malignant neoplasm involving the breast. "High LAMP3 expression is associated with lymph node metastasis and poor overall survival in patients with gastrointestinal cancer, breast cancer, and esophageal cancer." (PMID 39429383, 2024). "In breast cancer, LAMP3 was associated with tamoxifen resistance, radioresistance and inflammation, and its downregulation promoted the sensitivity of cisplatin in prostate cancer." (PMID 38146591, 2024). "In addition, LAMP3 overexpression in tissue promotes metastasis of breast cancer cells, while its increased expression is associated with poor overall survival in patients with gastrointestinal cancer, cervical cancer, and breast cancer." (PMID 40806007, 2025). "Increased expression of LAMP3 is reported to be associated with unfavorable prognosis of patients with various cancers such as laryngeal squamous cell carcinoma, gastrointestinal tumors, breast cancers, and cervical cancer." (PMID 39429383, 2024). "Moreover, LAMP3 is considered a suitable biomarker for breast cancer as it is associated with the progress regulating hypoxia, and its expression in epithelial cells is reported to evaluate the prognosis of esophageal squamous cell carcinoma." (PMID 36139498, 2022). "Moreover, PERK arm of the UPR facilitates the metastasis of breast cancer cells by activating lysosome-associated membrane protein 3 (LAMP3)." (PMID 31739582, 2019). "Furthermore, higher TRIB3 and ULK1 expression is associated with a poor prognosis in breast cancer while higher LAMP3 expression has been associated with lymph node positivity and hormone receptor negative breast cancers." (PMID 30248920, 2018). "Recent studies demonstrated high expression of lysosome-associated membrane protein 3 (LAMP3) in a variety of malignancies including esophageal squamous cell carcinoma, gastrointestinal cancer, breast cancer, and cervical cancer and its involvement in several biological activities of tumor cells." (PMID 28607528, 2017). "Additionally, hypoxia induces ER stress and unfolded protein response and was recently linked to migration and sphere formation in breast cancer cells by activation of the PERK/ATF4/LAMP3 arm under hypoxic conditions." (PMID 25849745, 2015). "In gastrointestinal cancer tissues, LAMP3 expression was not only elevated significantly compared with normal tissues, its high expression was also associated with poor overall survival in patients with gastrointestinal cancer, cervical cancer and breast cancers." (PMID 26263981, 2015). "In breast cancer cell lines, LAMP3 was induced by hypoxia in vitro and in vivo, and the correlation between mRNA expression level and lymph node metastasis implicated the hypothesis of a function of LAMP3 in the hypoxia-mediated metastasis in breast cancer." (PMID 26263981, 2015). "Previous reports showed that LAMP3 was expressed which depends on oxygen concentration and it contributed to tamoxifen resistance in breast cancer." (PMID 38146591, 2024). "Only in breast cancer patients undergoing lumpectomy and radiation therapy did those with high expression of LAMP3 have worse DFS and OS than those with low levels." (PMID 38146591, 2024). "The genes are associated with laryngeal cancer (MEOX2), cervical cancer (FGF7), oral cancer (DPT), breast cancer (CILP) or ovarian cancer (TMEM119) and LAMP3-positive dendritic cells are generally associated with cancer." (PMID 38671536, 2024). "In another study, ATF4 upregulated the expression of LAMP3 to promote cell migration in breast cancer cells under hypoxic conditions." (PMID 39090107, 2024). "Previous studies have demonstrated that knockdown of LAMP3 inhibits autophagy and increases tamoxifen sensitivity of breast cancer cells." (PMID 39834939, 2024). "In breast cancer, a recent report showed that recurrence‐free survival was better in patients with high mRNA levels of LAMP3 than in those with low levels in patients with basal or HER2‐positive subtypes." (PMID 36808888, 2023).
breast cancer (continued). "The prognostic value of LAMP3+ DCs has been evaluated in several cancer types, including the ovarian cancer, melanoma, breast cancer and lung cancer." (PMID 36808888, 2023). "Further, proteasome inhibition induces LAMP3 expression in an ATF4-dependent manner in breast cancer cells." (PMID 37062845, 2023). "Only during knockdown of PERK, ATF4 or LAMP3 can enhance the sensitivity of breast cancer cells to radiotherapy." (PMID 36675080, 2023). "Further, this TIMP-1-CD63 (LAMP3) signaling axis has been identified as playing a role in tumor metabolism of breast cancer cells by downstream upregulating aerobic glycolysis through carbonic anhydrase IX (CAIX) and thereby extending cell survival." (PMID 36551979, 2022). "Knockdown of PERK, ATF4 and LAMP3 led to a reduction in breast cancer cell migration, with more pronounced effects observed at 0.1% O2 compared with 1% O2." (PMID 34003246, 2021). "LAMP3 was suggested to play a role in detoxification of cisplatin in CRPC and associate with aggressive breast cancer." (PMID 33498739, 2021). "The PERK/ATF4 axis was demonstrated to activate lysosome-associated membrane protein 3 (LAMP3), resulting in the metastasis of breast cancer cells." (PMID 30282948, 2018). "PERK-ATF4 axis activates lysosome-associated membrane protein 3 (LAMP3), thereby facilitating metastasis of hypoxic breast cancer cells." (PMID 29430279, 2017). "In breast cancer xenografts, LAMP3 protein expression colocalizes with hypoxic areas and is associated with locoregional recurrence." (PMID 25362357, 2014). "Expression of LAMP3 protein in both dendritic cell and tumor epithelial cell had prognostic value in breast cancer." (PMID 25362357, 2014). "In this study, evidence is provided that UPR-induced LAMP3 can influence hypoxia-mediated cell migration of breast cancer cells." (PMID 23294542, 2013). "In this study the role of UPR-induced LAMP3 in hypoxia-mediated migration of breast cancer cells was examined." (PMID 23294542, 2013). "Overexpression of LAMP3 promoted invasion and metastasis in cervical cancer and breast cancer." (PMID 38146591, 2024). "In addition to radio-sensitization of breast cancer cells, knockdown of LAMP3 sensitizes cells to tamoxifen." (PMID 36675080, 2023). "LAMP3 knockdown also reduced spheroid invasion in a breast cancer cell line." (PMID 34003246, 2021). "Activation of this UPR branch may induce EMT under hypoxic stress where the PERK/ATF4/LAMP3 arm of the UPR increases breast cancer cell migration and invasion induced under moderately hypoxic condition (1% O2)." (PMID 33746610, 2021). "Furthermore, LAMP3 is correlated to the hypoxia regulation progress, which makes it a good biomarker for breast cancer, and epithelial LAMP3 expression is reported to be a prognostic biomarker for esophageal squamous cell carcinoma." (PMID 30008754, 2018). "Radiation treatment of breast cancer cells induces the PERK/ATF4/LAMP3 pathway." (PMID 30248920, 2018). "In addition, the protein expression of LAMP3 contributes to locoregional recurrence in breast cancer." (PMID 28607528, 2017). "However, LAMP3 expression has been observed in both DCs and epithelial cells in some cancers, and had a prognostic value in breast cancer." (PMID 26263981, 2015). "In addition, hypoxia was found to stimulate the migration of breast cancer cells via the PERK/ATF4/LAMP3-arm of the unfolded protein response, suggesting a role of ATF4 in cancer metastasis." (PMID 25078779, 2014). "In what way LAMP3 is involved in breast cancer metastasis and which role hypoxia may have in this process is unknown." (PMID 23294542, 2013). "Thus, the PERK/ATF4/LAMP3-arm of the UPR is an additional pathway mediating hypoxia-induced breast cancer cell migration." (PMID 23294542, 2013). "The PERK/ATF4/LAMP3 arm of the UPR might function as a new target for therapy combating hypoxia-induced metastasis in breast cancer." (PMID 23294542, 2013).
breast cancer (continued). "In addition, we found that LAMP3 has prognostic relevance in breast cancer." (PMID 23294542, 2013). "Therefore, we set out to determine whether the UPR can influence migration and invasion of breast cancer cells via LAMP3 under hypoxic conditions." (PMID 23294542, 2013). "Breast cancer cells and the human cervical cell line TCS both overexpressed LAMP3, which increased lymph node metastasis in vivo and in vitro, respectively." (PMID 38922530, 2024). "In breast cancer, radiotherapy triggers the PERK-pathway of the UPR, and this is induced by increased PERK protein levels, phosphorylated eIF2α, ATF4, and LAMP3." (PMID 36675080, 2023). "Overexpression of LAMP3 in the human cervical cell line TCS and breast cancer cells promoted cell migration in vitro and lymph node metastasis in vivo." (PMID 37062845, 2023). "In breast cancer, the PERK/ATF4/LAMP3-arm of the UPR is an additional pathway mediating hypoxia-induced tumor cell migration." (PMID 25078779, 2014). "Recent studies have demonstrated that increased expression of LAMP3 correlated with unfavorable prognosis of patients with esophageal squamous cell carcinoma, gastrointestinal stromal tumor (GIST), breast cancers, cervical cancer, and head and neck squamous cell carcinomas." (PMID 28607528, 2017). "Although the definite function of LAMP3 has not been identified, recent studies have identified that over expression of LAMP3 promoted metastasis of breast cancer cells." (PMID 26263981, 2015).
melanoma (22 papers, 2011 to 2024). A malignant, usually aggressive tumor composed of atypical, neoplastic melanocytes. "For instance, high density of LAMP3+ DCs has been associated with longer survival in melanoma and colorectal carcinoma, and a 3-gene transcriptional signature (LAMP3, CCL19, CCL22) correlates with increased survival in head and neck cancer." (PMID 39483484, 2024). "Such LAMP3+ DCs, identified in the brain metastases of melanoma patients, have been associated with increased overall survival." (PMID 37190135, 2023). "Besides, LAMP3 was also reported to be in the immunotherapy-response-associated signature of tertiary lymphoid structures in melanoma." (PMID 37082269, 2023). "As for mregDCs—firstly described in melanoma by their expression of DC-LAMP/LAMP3—they were associated with the local expansion of memory cytotoxic T-cells and the absence of lymph node metastasis, hypothesizing an anti-tumor activity for mregDCs." (PMID 37190135, 2023). "CD63, also named lysosome-associated membrane glycoprotein 3 (LAMP3), is a member of the tetraspanin superfamily demonstrated to shuttle between the plasma membrane and intracellular compartments and is overexpressed in pancreatic cancer, gastric cancer and melanoma." (PMID 32989604, 2020). "The relationship between LAMP3 and the response to anti‐PD‐1 monotherapy and anti‐PD‐1/anti‐CTLA‐4 combined therapy in melanoma patients showed that the survival of patients with high LAMP3 expression was better than those with low LAMP3 expression (p < 0.05)." (PMID 38146591, 2024). "Such LAMP3+ DCs have also been identified in the brain metastases of melanoma patients." (PMID 37190135, 2023). "The immunotherapeutic response in a cohort of PRJEB23709, the response group proved the higher LAMP3 expression level in LAMP3 with anti‐PD‐1 monotherapy and anti‐PD‐1/anti‐CTLA‐4 combined therapy in melanoma (p < 0.05)." (PMID 38146591, 2024).
cervical cancer (18 papers, 2014 to 2025). A primary or metastatic malignant neoplasm involving the cervix. "In cancer biology, e.g. overexpression of LAMP3 is associated with potential metastatic cervical cancer." (PMID 32150563, 2020). "Overexpression of LAMP3 has been shown to promote metastasis in cervical cancer xenografts and to associate with poor treatment outcome in clinical studies." (PMID 30294508, 2018). "In cervical cancer, expression of LAMP3 is associated with hypoxia and mediates hypoxia-driven nodal metastasis through regulating cell migration." (PMID 25362357, 2014). "LAMP3 overexpression is highly associated with metastatic potential and it has been proposed that LAMP3 may be an important prognostic biomarker for cervical cancer." (PMID 36016386, 2022). "By co-culturing a cervical cancer cell line with P. bivia, we confirmed that three out of the ten top predicted genes in the transkingdom network (lysosomal associated membrane protein 3 (LAMP3), STAT1, TAP1), all regulators of immunological pathways, were upregulated by this microorganism." (PMID 30294508, 2018). "For example, overexpression of LAMP3 is able to boost the metastasis of cervical cancer cell lines in vivo and in vitro." (PMID 38217544, 2024). "LAMP3 expression was relevant to poorer survival in patients with cervical cancer, head and neck squamous cell carcinoma, stomach cancer and colorectal cancer, while in non‐small cell lung cancer LAMP3 expression was relevant to better survival with patients." (PMID 38146591, 2024). "Our findings agree with a previous study, where LAMP3 mRNA was found to be highly expressed in 100% of cervical cancers." (PMID 36016386, 2022). "Lysosomal-associated membrane protein 3 (LAMP3), a hypoxia-inducible gene, is regulated by activation of the PERK/eIF2a/ATF4 arm of the UPR to promote lymph node metastasis in breast and cervical cancer." (PMID 33267910, 2020). "Co-culture of a cervical cancer cell line with P. bivia in our work showed that this bacterium indeed upregulates LAMP3 under anaerobic conditions." (PMID 30294508, 2018). "In the same cervical cancer work, we had performed siRNA perturbation of gene LAMP3 (GSE29009), which was one of the key gene-drivers of the antiviral subnetwork." (PMID 27737689, 2016). "LAMP3 overexpression promoted the metastasis in cervical cancer, and it may be a novel predictor of both gastric cancer and cervical cancer." (PMID 38146591, 2024). "Based on transkingdom network analysis and the result of the co-culture with a cervical cancer cell line, Prevotella is found to upregulate LAMP3, a key tumor driver, which plays a crucial role in cervical cancer by driving expression of multiple antiviral genes under anaerobic conditions." (PMID 39058300, 2024). "LAMP3 acted as a tumor promoter contributing to cervical cancer metastasis." (PMID 37868956, 2023). "LAMP3 was associated with increased migration in an overexpression model derived from a cervical cancer cell line, and an in vivo metastasis assay demonstrated that 9 of 11 LAMP3 overexpressing mouse models elicited a process of distal metastasis with invasion of the lymphovascular space." (PMID 36672296, 2023). "LAMP3 itself seems to play a crucial role in cervical cancer." (PMID 30294508, 2018). "In addition, high LAMP3 expression predicts poor survival in patients with cervix cancer and esophageal squamous cell carcinoma." (PMID 28607528, 2017). "Thus we analyzed if the direction of regulation of genes affected by LAMP3 siRNA in the cell line was corresponding to the sign of correlation between each gene and LAMP3 in four cervical cancer datasets (GSE7410, GSE9750, GSE6791, GSE7803)." (PMID 27737689, 2016). "In addition to this, the function of LAMP3 co-localization with hypoxic areas and regulating hypoxia-driven nodal metastasis was also observed in cervical cancer." (PMID 26263981, 2015). "In cervical cancer, only epithelial LAMP3+ expression was detected." (PMID 25362357, 2014).
cervical cancer (continued). "P. bivia has been shown to upregulate proinflammatory (LAMP3, STAT1, and TAP1) genes in cervical cancer." (PMID 35928983, 2022). "Lysosome-associated membrane protein 3 (LAMP3) is the third member of the LAMP family and its overexpression has been described to be involved in the progression of breast, ovarian and cervical cancers, but there has been an absence of research focusing on its role in UCEC." (PMID 38217544, 2024).